NLRP3 (NLR family pyrin domain containing 3)
Diseases named in the same sentence as NLRP3 in open-access papers (continued):
Sharing a sentence is not in itself a finding about the gene and the disease.
asthma (continued). "Activation of the NLRP3 inflammasome can result in excessive inflammation and tissue damage, contributing to chronic inflammatory diseases, such as asthma." (PMID 39065704, 2024). "In this study, we found that treating OVA-AAI mice with LY294002 significantly inhibited NLRP3 inflammasome activity in lung tissue, which is consistent with the PI3K–NLRP3 chain of action reported in asthma." (PMID 39834584, 2024). "Expression of the NLRP3 inflammasome has been associated with acute exacerbations of COPD and neutrophilic airway inflammation, worsening lung function, and poor asthma control." (PMID 39554494, 2024). "In this review we have highlighted the multifaceted involvement of IL-18 in asthma, from its interactions with other cytokines to its activation through inflammasome pathways, particularly NLRP3." (PMID 39554494, 2024). "Both clinical and experimental studies have shown that NLRP3 is present at high levels in the sputum and peripheral blood of patients’ asthma and in OVA-allergic airway inflammation (AAI) models." (PMID 39834584, 2024). "Mice with ovalbumin (OVA)-induced asthma presented with increased pulmonary NLRP3, caspase-1 and IL-1β expression, while the blockage of the NLRP3/caspase-1/IL-1β pathway attenuated bronchial inflammation in asthmatic mice." (PMID 39611173, 2024). "NLRP3 was found to be upregulated in AECs in mice with severe asthma induced by Chlamydia/Haemophilus respiratory infection combined with OVA challenge." (PMID 39611173, 2024). "In a separate severe asthma cohort, increased levels of NLRP3 pathway components were documented in sputum macrophages from the neutrophilic asthma endotype." (PMID 39554494, 2024). "Secondly, our study primarily focused on identifying new substances that inhibit the secretion of IL‐1β through NLRP3 in severe asthma." (PMID 38668995, 2024). "Another study reported that PI3K inhibition can reduce NLRP3 inflammasome activation in primary airway epithelial cells collected from an HDM-induced mouse model of asthma." (PMID 39834584, 2024). "Nonetheless, further investigations are required to elucidate the mechanisms by which RAGE influences DAMP release and how it promotes NLRP3 inflammasome activation in severe asthma." (PMID 36776857, 2023). "The role of DEK on mitophagy, NLRP3 inflammasome, and apoptosis of asthma model was further verified in DEK-knockout mice." (PMID 38274803, 2023). "Inhibition of NLRP3 inflammasome can prevent airway hyperreactivity and inflammation in mice with severe asthma by inhibiting the expression of IL-1β and Th-2." (PMID 36903624, 2023). "In a mouse model of asthma induced by house dust mite extract, inhibition of the NLRP3 inflammasome with MCC950 (i.e., CP-456,773) effectively reduced airway inflammation upon acute exposure to house dust mite extract." (PMID 36669831, 2023). "This study aimed to explore the influence of MUC1 on neutrophil airway inflammation in patients with asthma and verify the underlying mechanism associated with the TLR4/MyD88/NF-κB pathway and NLRP3 inflammasome-mediated pyroptosis." (PMID 37880668, 2023). "NLRP3 inflammasome activation has been shown to play a critical role in breaking tolerance to antigens and the induction of experimental asthma." (PMID 38044426, 2023). "Despite its role in pathogen clearance in the lung, persistent NLRP3 activation by environmental allergens and/or inhaled irritants has been shown to increase pulmonary inflammation and to lead to asthma exacerbation." (PMID 36677800, 2023). "Accumulating clinical and experimental evidence strongly implicate excessive NLRP3 inflammasome activation and IL-1β production in severe asthma pathogenesis, particularly, neutrophil-high, T2-low subtypes." (PMID 38044426, 2023). "This study is the first to identify a hitherto uncharacterized mechanism, i.e. the DEK/ATAD3A/DRP1 signaling axis, by which DEK promotes PINK1-Parkin mitophagy, NLRP3 inflammasome activation, and aggravates airway inflammation in asthma." (PMID 38274803, 2023).
asthma (continued). "The discovery of NLRP3 as a novel therapeutic target for the most effective management of severe asthma exacerbation has prompted researchers to investigate the natural compound curcumin, which is known for its anti-inflammatory properties." (PMID 36677800, 2023). "For example, Kim and co-workers found increased NLRP3 and IL-1β responses in steroid-resistant asthma patients." (PMID 38069047, 2023). "The mechanism of PINK1-Parkin-mediated NLRP3 inflammasome activation in asthma is largely controversial." (PMID 38274803, 2023). "NLRP3 inflammasome-mediated pyroptosis has been thought to be an important trigger of neutrophil airway inflammation in asthma." (PMID 37880668, 2023). "We previously showed that respiratory infections have important roles in initiating immune responses, including NLRP3 inflammasome-mediated IL-1β responses, in the asthmatic lung that promote severe, steroid-insensitive asthma." (PMID 38044426, 2023). "According to research, Acinetobacter baumanni activates the Nod-like receptor NLRP3 via caspase-1 to promote the release of IL-1β and TNFα from macrophages, thereby inducing asthma." (PMID 37180436, 2023). "It has been reported that mtROS and mtDNA can trigger the activation of the NLRP3 inflammasome in the airway remodeling of asthma." (PMID 38274803, 2023). "Unfortunately, such analyses were not feasible in the current study, which was designed to assess the differences of NLRP3 inflammasome priming and activation, and effectiveness of inflammasome inhibition, in systemic immune cells in asthma." (PMID 38044426, 2023). "Conclusively, DEK deficiency alleviates airway inflammation in asthma by down-regulating PINK1-Parkin mitophagy, NLRP3 inflammasome activation, and apoptosis." (PMID 38274803, 2023). "Increased NLRP3 and IL-1β responses correlate with increased neutrophil numbers, severity of airflow obstruction, and reduced asthma control in patients, the majority of which were on ICS maintenance therapy." (PMID 38044426, 2023). "We found low expression of NLRP3 mRNA in fully differentiated, mature bronchial epithelial cells from patients with asthma and control individuals at baseline or after RV infection." (PMID 37087523, 2023). "Simultaneously, Acinetobacter has several virulence factors, including toxins that form pores, and its outer membrane protein A induces dendritic cells to produce ROS, which can activate NLRP3 and promote immune responses such as asthma and allergic rhinitis." (PMID 37180436, 2023). "In Cluster 1 with higher cytokine levels, we also found increased expression of NLRP3 (NLR and pyrin domain containing 3), which is associated with asthma severity." (PMID 36864187, 2023). "DEK gene knockout, silencing, and targeted inhibitors down-regulated PINK1-Parkin-mediated mitophagy, NLRP3 inflammasome activation, and apoptosis, thereby improving airway inflammation in asthma." (PMID 38274803, 2023). "The relationship between NLRP3 and asthma was further cemented when the activation of NLRP3 was inhibited by some novel NLRP3 inhibitors or by silencing of NLRP3." (PMID 37251328, 2023). "The excessive and chronic activation of the NLRP3 inflammasome can lead to bacterial infections, asbestosis, silicosis, severe asthma, COPD, and cystic fibrosis." (PMID 38069047, 2023). "Sputum from neutrophilic asthmatics has been shown to exhibit elevated gene expression of NLRP3, caspase-1 and IL-1β and increased IL-1β protein concentration as compared to samples from eosinophilic asthmatics, patients with mild asthma or healthy controls." (PMID 37598239, 2023). "In animal models of asthma, NLRP3 inhibitors are still ineffective in controlling AHR and pulmonary inflammation." (PMID 36677800, 2023). "In a mouse model of asthma induced by ovalbumin, the NLRP3 inflammasome was activated, leading to increased IL-1 production, which was critical for the induction of a T helper 2 type of inflammatory allergic response in the airway." (PMID 36669831, 2023).
asthma (continued). "We now show that increased NLRP3 inflammasome-mediated IL-1β release from immune cells from humans with severe asthma can be pharmacologically inhibited with MCC950, demonstrating therapeutic potential for inflammasome inhibition in clinical settings." (PMID 38044426, 2023). "A large number of experiments have proved that the activation of NLRP3 inflammasome can be inhibited by inhibiting key targets upstream or downstream of the activation pathway, providing new ideas for the treatment of asthma." (PMID 36444628, 2022). "In the genotype of the NLRP3 rs12048215 locus, the IgE level of asthma patients with genotype AG was lower than that of patients with genotype AA." (PMID 36595748, 2022). "Another study showed that the levels of NLRP3 and caspase-1 in the airway of patients with a neutrophilic subtype of asthma were higher than those of healthy people." (PMID 36248872, 2022). "The review aims to describe and summarise the contribution of NLRP3 inflammasome to respiratory disorders development, including allergic rhinitis, asthma and chronic obstructive pulmonary disease (COPD)." (PMID 36203607, 2022). "NLRP3 and IL-18 protein levels of airway epithelial cells in lung biopsies of patients with asthma were found higher than those of healthy people." (PMID 36248872, 2022). "Recently, another specific NLRP3 inhibitor was tested in a murine model of asthma with promising results." (PMID 36189256, 2022). "At present, preventing the activation of NLRP3 inflammasome has become a hot spot in the treatment of severe asthma." (PMID 36248872, 2022). "With the accumulation of evidence supporting the implication of NLRP3 in asthma development, some authors had started to consider and test these inhibitors as potential asthma therapeutic tools." (PMID 36189256, 2022). "Although not entirely related to epithelial cells, BAL fluid from asthmatic patients at baseline exhibited higher NLRP3 protein content than healthy controls, suggesting a role for NLRP3 in asthma." (PMID 36189256, 2022). "Accumulating evidence has demonstrated that NLRP3 inflammasome is involved in the pathogenesis of airway inflammation and the process of airway remodeling in asthma." (PMID 35664352, 2022). "The distribution of NLRP3 rs10925023/MAVS rs7272495 haplotypes frequencies between asthma group and control group [n (%)]." (PMID 36595748, 2022). "The purpose of this study was to analyze the effects of NLRP3 and MAVS polymorphisms on the risk of asthma and the interactions between them." (PMID 36595748, 2022). "In a mouse model of OVA-induced neutrophilic inflammation in asthma, the current research found enhanced NLRP3 inflammasome activation." (PMID 35664352, 2022). "Thus Nlrp3 may be implicated in the pathogenesis of Th2-dominated diseases such as AR and asthma." (PMID 33707120, 2022). "Further studies in mice showed that the NLRP3 inflammasome was required for asthma development and expression of the cytokines IL-13, IL-5, and IL-6 in obese mice fed an HFD." (PMID 35806353, 2022). "Our findings showed that inhibiting the NLRP3/caspase-1/IL-1 pathway helped rebalance Th17/Treg cells in asthma patients." (PMID 35664352, 2022). "We summarize recent advances in the mechanism of NLRP3 inflammasome activation and regulation and its role in the pathogenesis of inflammatory lung diseases such as asthma and COPD." (PMID 36444628, 2022). "Of interest, the NLRP3 inflammasome has been reported to initiate pyroptosis, and the persistent NLRP3 activation is involved in severe asthma pathogenesis." (PMID 36213326, 2022). "The NLRP3 inflammasome plays a key role in the occurrence and development of a variety of inflammatory diseases, such as asthma, idiopathic lung disease, and radiation-induced pneumonia." (PMID 35761358, 2022). "The administration of MCC950 to a toluene diisocyanate-induced asthma model blocked the activation of NLRP3 and downregulated protein expression of caspase-1, IL1β, and IL18." (PMID 36189256, 2022).
asthma (continued). "Concomitantly, a multitude of clinical and experimental studies have demonstrated that the expression of NLRP3 inflammasome is significantly increased in patients with asthma and asthmatic murine models." (PMID 35664352, 2022). "Recent research has described the function of the NLRP3 inflammasome in various pulmonary diseases including respiratory infections, chronic obstructive pulmonary disease, and asthma." (PMID 35185385, 2022). "In another study using a murine asthma model, decreased expression of Nlrp3 was also found during airway inflammation." (PMID 33707120, 2022). "Tranilast, a drug currently approved in Japan for the treatment of asthma, has been recently rediscovered for its ability to inhibit the NLRP3 inflammasome, paving the way for its use in the treatment of other NLRP3-driven diseases." (PMID 35806353, 2022). "In particular, in vivo studies have shown that adipose tissue dysfunction can promote airway hyperreactivity, a cardinal feature of asthma that manifested depending on NLRP3 activity." (PMID 35806353, 2022). "Nlrp3 is the most studied structural subset of the inflammasome and plays an important role in the pathogenesis of numerous airway diseases such as asthma and acute lung injury." (PMID 33707120, 2022). "In a model of HDM-induced asthma, NLRP3 inflammasome even dampened Th2 responses through caspase-1 activation." (PMID 36189256, 2022). "Studies have found that NLRP3 inflammasomes are closely related to a variety of lung diseases, such as asthma, COPD, pulmonary fibrosis, acute lung injury and lung cancer." (PMID 36444628, 2022). "Since the imbalance of Th17, Treg cells, and their related cytokines play a vital role in the progression of asthma, we investigated the effects of NLRP3 and caspase-1 inhibitors on Th17-mediated immune responses in this murine model." (PMID 35664352, 2022). "Here, we summarize recent advances in the mechanism of NLRP3 inflammasome activation and regulation and its role in the pathogenesis of inflammatory lung diseases such as asthma and COPD." (PMID 36444628, 2022). "Mechanistically, we have provided evidence that ROS regulate allergic airway inflammation and asthma through controlling either autophagy/mitophagy or NLRP3 inflammasome activation." (PMID 36776398, 2022). "Most interestingly, the involvement of NLRP3 in CD4+ T cells in asthma, was elegantly confirmed by the restoration of the asthmatic phenotype in NLRP3 deficient mice by transferring WT OVA-specific Th2 cells." (PMID 36189256, 2022). "A large number of studies have shown that the NLRP3 inflammasome is involved in the process of chronic airway inflammation in asthma and COPD." (PMID 36444628, 2022). "At the same time, a potential therapeutic target for inhibiting the activation of NLRP3 inflammasome is proposed, which provides a new direction for the treatment of asthma and COPD." (PMID 36444628, 2022). "There were significant differences in the distribution of MVAS rs6515831 and NLRP3 rs10925023 genotypes between the asthma and healthy groups." (PMID 36595748, 2022). "NLRP3-targeted therapies provide potential and prospects for the treatment of related diseases including severe asthma." (PMID 36248872, 2022). "provided evidence indicating that a mitochondrial Ca2+/calmodulin-dependent protein kinase II mediates mitochondrial ROS production, which stimulates NLRP3 inflammasome activation in the airway epithelium and promotes asthma development." (PMID 36189256, 2022). "Recent reports have shown that NLRP3-related inflammatory response is a key driver of asthma pathogenesis and the allergen Der f1 induces bronchial asthma by mediating caspase-1-dependent pyroptosis through the NLRP3 pathway." (PMID 35967302, 2022). "NLRP3 inflammasome is usually regarded as an inhibitor in M2 activation; however, an increased number of M2 and the activation of NLRP3 inflammasome appear simultaneously in asthma patients." (PMID 35974386, 2022).